CRP (C-reactive protein)
Diseases named in the same sentence as CRP in open-access papers (continued):
Sharing a sentence is not in itself a finding about the gene and the disease.
Obesity (continued). "In human cohorts, CLS-B positively correlates with older age, obesity, dyslipidemia and higher levels of glucose, insulin, C-reactive protein and IL-6." (PMID 34294716, 2021). "The mean values for CRP, sICAM, and leptin were significantly higher in the children with obesity and adiponectin levels were significantly lower." (PMID 33665176, 2021). "Our findings are consistent with this, but only in women with obesity (who had higher initial values of CRP) and only in women with oxygen uptake up to 20 mL/(kg×min)." (PMID 33255278, 2020). "SAH, hypertriglyceridemia, and high CRP level were statistically associated with T2DM in class II and III obesity." (PMID 32498226, 2020). "Despite normal maternal oGTT (oral glucose tolerance test) levels, maternal overweight and obesity in pregnancy are characterized by insulin resistance and increased levels of inflammatory markers, i.e., IL-6 and CRP." (PMID 32012940, 2020). "Separately, in a clinical trial where adults with obesity and risk for insulin resistance consumed a cocoa beverage (vs. a low-flavanol control beverage) for five consecutive days, ICAM-1, IL-6, and C-reactive protein were reduced after a 75-g glucose load." (PMID 32605005, 2020). "Univariate analysis showed that risk factors for severe illness were obesity (BMI ≥ 28 kg/m2), presence of type 2 diabetes, lactate dehydrogenase (LDH) > 250 U/L, CRP > 10 mg/L, and ALB < 35 g/L." (PMID 32384078, 2020). "Only higher levels of CRP in individuals with obesity (p = 0.022) and higher Gal-3 with COPD (p = 0.023) were observed." (PMID 32695109, 2020). "A meta-analysis of eight studies showed a positive correlation of chemerin with body mass index (BMI), total cholesterol, fasting insulin, and C-reactive protein (CRP) in obesity or metabolic syndrome." (PMID 33228201, 2020). "Prevalence of elevated CRP and overweight/obesity by urban vs. rural location and maximum categories of the built environment (and tests of significance, p-value)." (PMID 33141863, 2020). "Almost one-third of the participants in our study had elevated CRP levels, which is in line with other studies that report between 1.5 and 15 mg/l for participants with obesity." (PMID 32154197, 2020). "Indoor cycling further improved lipid metabolism, especially in women with obesity, and reduced levels of the inflammatory marker CRP." (PMID 33255278, 2020). "Since obesity is well known to induce systemic chronic low-grade inflammation, we next analyzed the influence of BMI on the steady-state CRP and IL-6 levels." (PMID 32190093, 2020). "Similar results were obtained for correlation with markers of obesity (insulin, CRP, and leptin) with estradiol and estrone (−0.15 to 0.12; p = 0.11–0.82)." (PMID 32566743, 2020). "Surrogate inflammatory markers such as C-reactive protein and cytokines such as IL-6 have been used as predictive markers for type-2 diabetes mellitus in children with obesity." (PMID 32528415, 2020). "Our elevated CRP levels among the three obesity classes confirmed the link between inflammation and increased CRP levels in circulation of individuals with obesity." (PMID 32893859, 2020). "We included CRP as an exposure variable as high levels are assumed to promote the incidence of MetS components and of obesity, as previously shown in IDEFICS children." (PMID 32943762, 2020). "In the current study, the serum levels of TNF-α, CRP, IL-6, IL-12, sVCAM-1 and sICAM-1 were evaluated with the progression of obesity classes I–III." (PMID 32893859, 2020). "Remarkably, this meta-analysis showed that placebo group favored the glucose and CRP levels, which are correlated negatively with obesity-related symptoms and inflammatory responses." (PMID 32610476, 2020). "In a multivariate analysis study carried out in Mediterranean women with obesity, BMI and WC were independently correlated with hs-CRP concentration." (PMID 33182500, 2020).
Obesity (continued). "Regarding the inflammatory markers, we observed significantly elevated levels of CRP among the three obesity groups versus the normal control group." (PMID 32893859, 2020). "Association between CDV and hs-CRP quartiles in Isfahan Cohort with Logistic regression model in patients with dyslipidemia, DM, HTN, obesity and cigarette smoking." (PMID 32489776, 2020). "Vernarelli and Lambert reported that dietary flavonoid consumption was inversely correlated with the severity of obesity and serum CRP levels." (PMID 33195370, 2020). "In the rural sample, obesity also increased the odds of having increased triglyceride and Hs-CRP levels, while in the urban sample, high blood glucose was positively associated with obesity." (PMID 33178661, 2020). "Those with elevated CRP had a 1.74 higher chance of reporting LBP, which had an additive effect on risk of LBP when coexisting with obesity." (PMID 34466546, 2020). "Total SOD activity was negatively correlated with parameters elevated in obesity: TChol, TG, CRP, insulin concentration, BMI, and HOMA-IR indices." (PMID 32709094, 2020). "C-reactive protein (CRP) is an acute-phase reactant associated with cardiovascular disease, type 2 diabetes and obesity." (PMID 33086688, 2020). "Noteworthy, individuals with obesity showed higher (p < 0.01) circulating levels of the inflammatory markers CRP and fibrinogen." (PMID 32283761, 2020). "There are scant descriptive statistics, particularly of CRP but also of overweight or obesity, in countries such as Tanzania." (PMID 33141863, 2020). "Univariate linear regression analysis showed different growth rates between the CRP rats and the control rats, and that the difference appears around 11 weeks old, indicating that they developed adult-onset obesity." (PMID 32154244, 2020). "We found both elevated CRP and overweight/obesity decreased from the richest to poorest quintiles, but this decrease was more linear for weight status than for CRP." (PMID 33141863, 2020). "This study demonstrates that the long-term chronic CRP elevation will lead to adult-onset obesity, which is based on results of the CRP transgenic rat model with low levels of human CRP expression." (PMID 32154244, 2020). "One study also used a healthy control group and concluded that pre-intervention CRP and IL-6 levels were significantly higher in obesity versus controls." (PMID 32977711, 2020). "First, our analysis provides prevalence of elevated levels of CRP and overweight/obesity among women in Tanzania." (PMID 33141863, 2020). "Of note is the association between obesity and type 2 diabetes and increased IL-6, TNF-α, and C-reactive protein (CRP) levels." (PMID 33027912, 2020). "All participants, both Teens and PACs in this study, met criteria for obesity and had baseline CRP > 14.3 nmol/L." (PMID 33079935, 2020). "Individuals with obesity present high concentrations of CRP, an acute phase inflammatory marker mainly produced in the liver, and this process is regulated predominately by IL-6." (PMID 32893859, 2020). "Our study showed that in the group with obesity, serum concentrations of calprotectin and chemerin, as well as CRP were significantly higher as compared with the controls." (PMID 33081030, 2020). "Molecular markers of obesity (e.g. IL-6, CRP, leptin, interleukin 1 beta [IL-1β]) increase the generation of myeloid-derived suppressor cells (MDSCs)." (PMID 33123173, 2020). "Pro-inflammatory markers, such as interleukin-6 (IL-6), tumor necrosis factor α (TNFα), and C-reactive protein (CRP), elevate in response to infection, tissue damage, and in active stressed states such as obesity." (PMID 33004039, 2020). "In conclusion, CRP derived from PVAT was significantly increased in obesity and promoted neointimal hyperplasia after vascular injury, partially through CRP-mediated enhancement of adventitial macrophage infiltration." (PMID 32046736, 2020).
Obesity (continued). "Several markers of obesity and inflammation, including CRP (marker of inflammation), insulin (marker of insulin resistance), and leptin (marker of adiposity) were measured to evaluate their potential associations with estradiol or estrone levels." (PMID 32566743, 2020). "The increase in CRP level is in line with the well-established role of chronic inflammation in obesity-induced pathologies." (PMID 32190093, 2020). "Obesity elevated levels of C reactive protein and IL-1β in the blood, just increasing the development risk of T2DM." (PMID 32938466, 2020). "CRP is an important inflammatory marker, which reinforces the finding of this study that the higher degree of obesity compromises bone health due mainly to low-grade inflammation." (PMID 32992832, 2020). "Moreover, obesity status is associated with insulin resistance, higher blood free fatty acids, and chronic micro-inflammatory status, which mediated and affected by several pro-inflammatory cytokines, such as C-reactive protein (CRP) and tumor necrosis factor-α." (PMID 33552985, 2020). "Risk factors associated with lower total vertebral column BMD were previous fracture (p = 0.007), greater BMI obesity (≥50 kg/m2) (p = 0.022), vitamin D insufficient intake (p = 0.039), elevated CRP levels (p = 0.049) and insufficient serum zinc (p = 0.010)." (PMID 32992832, 2020). "The relationship between CRP, a protein of acute phase response, and overweight/obesity has been intensively investigated." (PMID 33081030, 2020). "Herein, data presented in our study highlight the alterations in the serum levels of TNF-α, CRP, IL-6, IL-12, sVCAM-1 and sICAM-1 with the progression of obesity among Egyptian females." (PMID 32893859, 2020). "The interactions of CRP gene SNP rs1130864 and rs3093059 with obesity were significant on IMT (P<0.001), serum hs-CRP (P <0.01) and fibrinogen level (P<0.001)." (PMID 32214403, 2020). "In the group with obesity, serum calprotectin, chemerin, and CRP levels were significantly higher as compared with the normal body weight children." (PMID 33081030, 2020). "It has been shown that the CRP value was higher in patients with obesity and also that CRP elevation correlated with body weight gain and adiposity in both adults and adolescents." (PMID 33081030, 2020). "Collectively, we observed a lower expression of TUG1 in obese women and its inverse correlation with obesity indices, hs-CRP, and creatinine levels." (PMID 32368256, 2020). "As expected, our results indicate a significantly higher baseline level of the inflammatory marker CRP in women with obesity compared to those with normal weight." (PMID 33255278, 2020). "Although multiple studies have shown higher CRP levels in females compared to males, there are limited studies about sex differences in children with obesity." (PMID 32528415, 2020). "Thinking about the signaling passage from low-grade inflammation—gut flora—obesity, it is likely that CRP is upstream to the low-grade inflammation by bringing in a pseudo inflammatory signal for the low-grade inflammation." (PMID 32154244, 2020). "Both inflammatory markers (CRP, TNF-α) were positively associated with waist circumference (obesity indicator) in the study subjects." (PMID 32670417, 2020). "Our intervention also seems to mitigate the inflammatory effects of obesity, as shown by the decrease in CRP, in line with previous research." (PMID 32899955, 2020). "Numerous studies have demonstrated that HFD feeding and obesity contribute to increases in circulating cytokines and acute phase proteins such as CRP, TNFα, and IL-6." (PMID 32823541, 2020). "Abdominal obesity can also lead to elevated CRP as a result of macrophage infiltration in adipose tissue that release inflammatory signals and cytokines, which has been shown in children with obesity from 6 years onwards." (PMID 32943762, 2020).
Obesity (continued). "Using the National Health and Nutrition Examination Survey (NHANES), a nationally representative cross-sectional survey, Cycles 1999–2010, I examined how educational attainment impacts Black women’s rate of obesity and C-reactive protein levels (N = 2685)." (PMID 31728932, 2020). "We hypothesized that the three most common characteristics of OSAS (severity of OSAS, sex, and obesity) may have an interaction effect on the risk of cardiovascular events as determined by the serum levels of the three most representative inflammatory markers (CRP, IL-6, and TNF-α)." (PMID 32629899, 2020). "This obesity-induced inflammation will elevate the level of C-reactive protein, ICAM, and resistin, which subsequently increases the level of cholesterol in the blood." (PMID 33029159, 2020). "The obesity phenotype is confirmed by whole-body magnetic resonance imaging (MRI), in which the total fat mass is 6- to 9- fold higher in the CRP rats than the control rats." (PMID 32154244, 2020). "The joint effects of high hs-CRP and overweight/obesity on IR were greater than would be expected from the effects of the individual exposures alone." (PMID 33116232, 2020). "It has been demonstrated that obesity is related to CRP levels and that adipose tissue likely modulates CRP levels." (PMID 33255278, 2020). "The inflammatory reaction is also an important predictor of MetS and usually accompanied with obesity, which is usually performed as a low grade, systemic inflammation, such as C-reactive protein." (PMID 30679939, 2019). "Our findings suggest a significant association of lower scores in the physical domain of quality of life and the presence of obesity with high CRP serum levels." (PMID 30728031, 2019). "Studies have reported that individuals with obesity had higher CRP serum concentrations compared with those of normal weight." (PMID 30674938, 2019). "The urinary CRP and 8-isoprostane significantly correlated with the obesity measures (body mass index, waist circumference, and waist-to- height ratio) and ET-1, inflammatory, and oxidative markers." (PMID 31737180, 2019). "Further, obesity is more strongly correlated with elevated high-sensitivity C-reactive protein levels in women than in men." (PMID 31118920, 2019). "A series of repeated measure analyses were performed using General Linear Models to discern the effect of obesity on each iron indicator; iron intake, hepcidin, and C-reactive protein were successively introduced as covariates." (PMID 30909605, 2019). "In the current study, higher hs-CRP level was observed in obesity groups include MHO and MUO comparing to MHNH among both genders younger than 45 years old and among women older than 45 years old." (PMID 31770376, 2019). "Insulin resistance, apoptotic marker M30, hs-CRP, and IL-6 were all elevated in adolescents with obesity." (PMID 31120986, 2019). "We also present ROC curves of high pre-RT CRP and/or obesity in predicting RT-related pain for (A) all, (B) NHW, (C) HW, and (D) AA patients and their corresponding area under the curve (AUC)." (PMID 31138314, 2019). "Women, as well as current and former smokers with overweight or obesity, had higher odds of elevated CRP concentration." (PMID 31052485, 2019). "Insulin resistance, apoptotic marker M30 level, hs-CRP, and IL-6 were all elevated in adolescents with obesity." (PMID 31120986, 2019). "The level of urinary CRP and 8-isoprostane significantly increased as the obesity measures increase and correlated with ET-1, inflammatory, and oxidative stress markers." (PMID 31737180, 2019). "Although the combined training had a positive effect on lipid metabolism and significantly reduced CRP levels, only endurance training favorably changed indicators of endothelial function in women with obesity." (PMID 31694237, 2019). "For both sexes, individuals with incomplete elementary school, light intensity of physical activity, current smokers and obesity presented higher median CRP levels." (PMID 31314878, 2019).
Obesity (continued). "Severe obesity (body mass index ≥35 or ≥40 after January 1, 2017, as indicated with a procedure-fee modifier), chronic inflammation (all measures of C-reactive protein >10 mg/L), and a surrogate measure of insulin resistance." (PMID 31469399, 2019). "In this context, the aim of the present study was to assess the associations of CRP with risk of incident T2DM and to determine the joint effect of obesity and hypertension in these associations in a large-scale population-based Korean cohort." (PMID 30872696, 2019). "It is possible that these foods may have a direct association with CRP, under the assumption that the high glycemic index of ultra-processed products could stimulate the entire chronic inflammation cascade, along with an indirect association mediated by obesity." (PMID 31314878, 2019). "Previous findings have shown that hsCRP is an independent risk factor of obesity and T2DM and hs-CRP is closely related to DN." (PMID 31281843, 2019). "The blue line is for obesity (BMI ≥ 30 kg/m2), the red line is for pre-RT CRP ≥ 10 mg/L, and the green line shows the combined effect of obesity and pre-RT CRP ≥ 10 mg/L." (PMID 31138314, 2019). "This study investigated the relationship between phytate intake and the odds of elevated CRP concentration among participants 20 years and older with overweight or obesity in the NHANES 2009/2010 survey cycle." (PMID 31052485, 2019). "Differences in thalamic, insula and amygdalar-hippocampal GMV have not been reported in the meta-analysis, but were found in univariate analysis of obesity-related factors such as CRP, HbA1c, and BMI." (PMID 31427957, 2019). "The important aspect of this study is to demonstrate that urinary CRP and 8-isoprostane showed a positive correlation with obesity measurements and inflammatory, oxidative stress, and endothelial dysfunction markers." (PMID 31737180, 2019). "High adiponectin to CRP ratio is regarded as an indicator of the favorable metabolic and anthropometric profiles in obesity/T2D." (PMID 31718015, 2019). "Obesity, in particular, is associated with increased pro-inflammatory markers such as IL-6, TNF-α and c-reactive protein (CRP)." (PMID 31212761, 2019). "Another important finding was the association of parameters representing visceral obesity with C-reactive protein levels, since obesity and IR contribute to the low-grade chronic inflammatory state in SOP." (PMID 31365630, 2019). "The blue line represents obesity (BMI≥30), the red line represents pre-RT CRP ≥10 mg/L, and the green line presents the combined effect of obesity and pre-RT CRP ≥ 10 mg/L." (PMID 31138314, 2019). "Chronic inflammation markers (hs-CRP and IL-6) and apoptotic marker M30 level were all positively correlated to the degree of obesity." (PMID 31120986, 2019). "Circulating Serum C-reactive protein (CRP) is involved in the genesis and development of obesity as well." (PMID 30854010, 2019). "Positive correlations were found between CRP and obesity related indicators, such as BMI (Rho = 0.664, p < 0.0001), body weight (Rho = 0.554, p < 0.0001), and %BF (Rho = 0.612, p < 0.0001; n = 52)." (PMID 30704070, 2019). "Controlling for non-normality of the CRP distribution, and for the strong positive correlation between CRP and obesity, we found that the case–control difference in CRP remained significant only for the subgroup of treatment-resistant patients." (PMID 29764522, 2019). "In subjects with obesity, CRP sensitivityincreases along with increased BMI, while lower specificity is seen in thesesubjects." (PMID 29513800, 2018). "In terms of cytokines, plasma IL-6 (p < 0.01) and CRP (p < 0.0001) were significantly elevated with pregravid obesity." (PMID 30131724, 2018). "In the present study, the increase of CRP among patients with AA was seenin the subset of individuals with obesity when correlated to normal or lean BMI." (PMID 29513800, 2018).